MIR222 (microRNA 222)
Synonyms: hsa-mir-222; MIRN222; miRNA222; mir-222
Gene: MicroRNA gene on chromosome X (45,747,015 to 45,747,124, reverse strand). Ensembl gene ENSG00000207725.
Gene Ontology:
Cellular component: RISC complex
Homologues: Orthologues: chimpanzee ptr-mir-222 (100% identical), macaque mml-mir-222 (99% identical), rat Mir222 (84% identical), rabbit MIR222 (82% identical), dog MIR222 (80% identical), zebrafish dre-mir-222a (75% identical), mouse Mir222 (69% identical), pig ssc-mir-222 (69% identical), guinea pig MIR222 (67% identical), tropical clawed frog xtr-mir-222 (49% identical). Paralogues in human: MIR221 (45% identical).
Diseases named in the same sentence as MIR222 in open-access papers:
MIR222 is named in the same sentence as 14 diseases in open-access papers, as found by Europe PMC text mining. Sharing a sentence is not in itself a finding about the gene and the disease. The quoted sentences say what the papers report.
Obesity (2 papers, 2021 to 2022). Accumulation of substantial excess body fat. "The adipocyte-specific inhibition of Mir221/Mir222 expression protected the mice fed with HFHS chow from the obesity." (PMID 35046889, 2021). "Mir221 and Mir222 are paralogous genes and share the common seed sequence and Mir221/222AdipoKO mice fed with HFHS chow demonstrated resistance to the development of obesity compared with Mir221/222flox/y." (PMID 35046889, 2021). "Overall, the upregulation of MIR222 could not only inhibit the expression of tumor suppressors such as target genes DIRAS3 and DCTN6 in prostate cancer but also prove that obesity has a strong correlation with cancer metastasis." (PMID 35164166, 2022). "Although miR-221-3p and miR-222-3p are differentially expressed in sera and adipose tissues, the functional in vivo experiments to elucidate the roles of Mir221 and Mir222 in obesity has not been reported." (PMID 35046889, 2021).
breast carcinoma (1 paper, 2024). "MIR221 and MIR222 were identified as regulators of epithelial‐to‐mesenchymal transformation (EMT) in breast cancer, contributing to the progression and metastasis of cancer." (PMID 39210544, 2024).
colitis (1 paper, 2025). Inflammation of the colon. "Mir222, characterized in models of inflammation-associated CC, including colitis-induced carcinogenesis, promotes tumor progression by enhancing inflammatory signaling and oxidative stress in the intestinal mucosa." (PMID 40869212, 2025). "Suppression of Mir222 ameliorates colitis and reduces inflammation-driven tumor growth, highlighting a direct mechanistic link between intestinal inflammation and CC progression mediated by Mir222." (PMID 40869212, 2025).
diabetes (1 paper, 2025). "The transfer of Mir221 and Mir222 via vascular smooth muscle cells – derived exosomes from diabetes affected vascular inflammation." (PMID 39245438, 2025).
glioblastoma (1 paper, 2025). The most malignant astrocytic tumor (WHO grade IV). "Elevated levels of Mir221 and Mir222 in glioblastoma promote cell survival, while reducing the levels of these miRNAs leads to increased apoptosis through the upregulation of BBC3/PUMA." (PMID 39245438, 2025).
Intellectual disability (1 paper, 2018). "It has been suggested that MIR222, with or without MIR221, is a plausible candidate to cause intellectual disability associated with X-linked retinal dystrophy in the Xp11.3 deletion syndrome." (PMID 30567555, 2018).
metastatic disease (1 paper, 2025). "The association of Mir222 with metastatic disease and inflammatory bowel pathology suggests it may act as a bridge between chronic intestinal inflammation and tumorigenesis." (PMID 40869212, 2025).
Sepsis (1 paper, 2024). Sepsis is defined as life-threatening organ dysfunction caused by a dysregulated host response to infection. "Additionally, Tnf has been reported to be a direct target of Mir221 and Mir222 in sepsis in macrophages." (PMID 39235454, 2024). "Recently, a study reported a role for Mir222 in targeting Brg1, an SWI/SNF chromatin remodeling component, leading to repression of inflammatory cytokine expression in sepsis." (PMID 39235454, 2024). "Under nonresolving inflammatory signals, such as in sepsis, the overexpression of Mir222 contributes to morbidity by targeting Smarca4, a chromatin remodeling component that participates in the SWI/SNF complex." (PMID 39235454, 2024).
cancer (3 papers, 2021 to 2024). A tumor composed of atypical neoplastic, often pleomorphic cells that invade other tissues. "Mir221 and Mir222 demonstrated the angiogenic activities in vascular cells and cancers, however, we did not observe the angiogenesis activities in WATs in Mir221/222AdipoKO mice." (PMID 35046889, 2021).
tumor (2 papers, 2024 to 2025). "Its modulation in preclinical inflammation-driven tumor models reinforces the hypothesis that changes in circulating Mir222 could indicate a pro-tumorigenic inflammatory milieu, detectable even prior to overt malignancy." (PMID 40869212, 2025).
cardiovascular diseases (1 paper, 2025). "Mir221 and Mir222 have been reported to be closely related to inflammation and the pathogenesis of cardiovascular diseases." (PMID 39245438, 2025).
MIR222 also shares sentences with these, for which no sentence is quoted: Arthritis (1 paper); neuroblastoma (1); prostate carcinoma (1).